PDZD7 (PDZ domain containing 7)
Description:
In cochlear developing hair cells, essential in organizing the USH2 complex at stereocilia ankle links. Blocks inhibition of adenylate cyclase activity mediated by ADGRV1.
Synonyms: PDZK7; FLJ23209; bA108L7.8; DFNB57
Tractability: Antibody: its Gene Ontology location is reachable by antibodies, with medium confidence. PROTAC: its protein half-life has been measured.
Gene: Protein-coding gene on chromosome 10 (101,007,679 to 101,032,295, reverse strand). Ensembl gene ENSG00000186862.
Subcellular location: Cell projection, cilium; Nucleus; Cell projection, stereocilium
Subcellular location (Human Protein Atlas): Nucleoplasm; Primary cilium; Basal body
Gene Ontology:
Molecular function: protein binding; identical protein binding
Biological process: auditory receptor cell development; auditory receptor cell stereocilium organization; detection of mechanical stimulus involved in sensory perception of sound; establishment of protein localization; inner ear receptor cell differentiation; sensory perception of sound
Cellular component: cilium; extracellular region; nucleus; plasma membrane; stereocilia ankle link; stereocilia ankle link complex; stereocilium; stereocilium tip; plasma membrane bounded cell projection; USH2 complex
Genetic constraint (gnomAD): Loss-of-function variants: 71 observed, 81.81 expected, observed/expected ratio (o/e) 0.87, 90% interval 0.72 to 1.06. The upper end of that interval is the gene's LOEUF score, 1.06, which puts it in group 4 of 6, group 1 being the genes least tolerant of losing a copy. Missense variants: 1,486 observed, 1,386.1 expected, observed/expected ratio (o/e) 1.07, 90% interval 1.03 to 1.12. Synonymous variants: 593 observed, 555.71 expected, observed/expected ratio (o/e) 1.07, 90% interval 1 to 1.14.
Gene-disease validity (ClinGen):
ClinGen rates the evidence that PDZD7 causes each of these diseases.
hearing loss, autosomal recessive (autosomal recessive): Definitive.
Homologues: Orthologues: chimpanzee PDZD7 (98% identical), rat Pdzd7 (83% identical), mouse Pdzd7 (83% identical), dog PDZD7 (81% identical), macaque PDZD7 (51% identical), tropical clawed frog pdzd7 (30% identical). Paralogues in human: WHRN (20% identical), USH1C (16% identical).
Diseases named in the same sentence as PDZD7 in open-access papers:
PDZD7 is named in the same sentence as 23 diseases in open-access papers, as found by Europe PMC text mining. Sharing a sentence is not in itself a finding about the gene and the disease. The quoted sentences say what the papers report.
Usher syndrome (20 papers, 2012 to 2025). A syndromic diseae characterized by the association of sensorineural deafness (usually congenital) with retinitis pigmentosa and progressive vision loss. "Subsequently, heterozygous variants in PDZD7 were identified as a modifier of retinal disease and a contributor to digenic Usher syndrome." (PMID 35715776, 2022). "Although, the gene encoding PDZD7 protein was originally defined as a modifier of retinal disease and a contributor for Usher syndrome, but this interpretation was revised according to the recent studies." (PMID 33530996, 2021). "PDZD7 gene was initially described as a modifier of the retinal phenotype in Usher syndrome; more recently however, it has been shown to cause autosomal recessive NSHL." (PMID 28173822, 2017). "In Usher syndrome patients with biallelic USH2A variants, another heterozygous PDZD7 variant causes earlier-onset and more severe retinal disease." (PMID 35715776, 2022). "Furthermore, in three clinical cases of USH, heterozygous pathogenic variants of PDZD7 were identified as possible USH disease modifiers and contributors to digenic Usher syndrome." (PMID 35353227, 2022). "These three scaffolding proteins are Whirlin (DFNB31), Harmonin (Ush1C) and the PDZ domain containing protein 7 (PDZD7), a deafness protein associated with the Usher syndrome." (PMID 33853521, 2021). "For instance, CAMK2G and PDZD7 are involved in Usher Syndrome the most common condition leading to deafness and blindness, as well as DNMT1 has a role in DNMT1-Related Dementia, Deafness, and Sensory Neuropathy and LRTOMT in deafness." (PMID 28993790, 2017). "Unlike CDH23 and PDZD7, which cause non-syndromic hearing loss or Usher syndrome presenting as non-syndromic hearing loss during childhood, PTPN11 is associated with NS1, which shows a variety of phenotypes in multiple organs." (PMID 35248088, 2022). "PDZD7 may act as a modifier gene for USH, but HARS, ABHD12, CIB2, CEP250, CEP78, ESPN, and ARSG could be grouped in a separate syndromic “deaf–blindness” category, to avoid diagnostic pitfalls and misinformation during genetic counseling for Usher syndrome." (PMID 35353227, 2022). "Pathogenic PDZD7 variants have been identified in individuals with AR non-syndromic hearing loss and it has been suggested that PDZD7 variants may also modify the severity of Usher syndrome." (PMID 35911904, 2022). "Although Usher syndrome (USH) has traditionally been characterized as a monogenic and genetically heterogeneous disorder, emerging evidence points to digenic inheritance involving interactions between USH genes such as PDZD7/USH2A in mice and humans." (PMID 40360853, 2025). "Moreover, PDZD7 has been suggested to be a contributor to digenic Usher syndrome type IIC and a modifier in patients with Usher Syndrome (USH) Type IIA." (PMID 35715776, 2022).
deafness (14 papers, 2016 to 2023). An inherited or acquired condition characterized by the complete loss of the ability to hear from one or both ears. "PDZD7 is a deafness-causing gene, and a previous report has associated PDZD7 mutations with USH, DFNB57, and autosomal recessive non-syndromic hearing loss (ARNSHL)." (PMID 33937240, 2021). "This structural and biochemical characterization of the PDZD7 HHD region provides mechanistic explanations for human deafness-causing mutations in PDZD7." (PMID 33937240, 2021). "Noticeably, the human deafness mutation (p.525_533delDQERGRALLinsV in PDZD7) locates adjacent to the HHD region, implying its involvement with hearing loss." (PMID 33937240, 2021). "PDZD7 is an important deafness gene, whose mutations are associated with syndromic and nonsyndromic hearing loss." (PMID 29796015, 2018). "WES identified a NSHL-causing splice variant in an autosomal recessive deafness gene PDZD7 which resided in a linkage region and affected three of the children." (PMID 28173822, 2017). "Interestingly, we showed that the stability and binding properties of the PDZ tandem are affected by two deafness-causing mutations located in the binding grooves of PDZD7 PDZ domains." (PMID 35836927, 2022). "Finally, we characterized the effect of the two deafness associated variants on the protein stability and on complex formation, disrupting the interaction between full-length PDZD7 and ADGRV1 β subunit, underlying potential defects in hair bundle morphogenesis." (PMID 35836927, 2022). "As a result, mutations in PDZD7 can cause non-syndromic recessive hearing impairment and also interrupt organization of cells and disrupt the MET process, causing SNHL and deafness as seen in USH." (PMID 33193648, 2020). "Originally identified as a modifier gene for Usher syndrome type 2 genes, PDZD7 has more recently been identified as a nonsyndromic deafness gene itself." (PMID 27525485, 2016). "We conclude that G103R disrupts quaternary USH2 protein complex assembly and phase separation by eliminating the interaction between PDZD7 and USH2A, which may be one of the mechanisms underlying deafness." (PMID 36964137, 2023). "Two deafness-causing mutations of the same amino acid substitution are located at the same position in the binding groove of the first (G103R) and second (G228R) PDZ domains in PDZD7." (PMID 35836927, 2022). "Sequence analysis showed that two deafness-associated mutation sites in Whirlin (V460 and R490, NCBI Clinvar database, VCV000364688, and VCV000156029) are conserved between Whirlin and PDZD7, which are corresponding to V594 and R624 in PDZD7." (PMID 33937240, 2021). "However, several studies have shown the digenic inheritance of deafness caused by mutations in USH genes and USH modifier PDZD7 in mice and humans." (PMID 33193648, 2020). "PDZD7 is an important deafness gene, whose mutations contribute to syndromic as well as nonsyndromic hearing loss." (PMID 29796015, 2018). "In addition to GRXCR2 and taperin, several proteins linked to deafness are concentrated at or near the stereocilia base, including Fam65b, PTPRQ, CLIC5, radixin, and PDZD7." (PMID 30380417, 2018). "A first-generation inherited hearing loss panel with 55 deafness genes failed to establish genetic diagnosis of NSHL since PDZD7 had not been associated with NSHL and due to the unusual presentation the skeletal phenotype eluded a definite clinical diagnosis." (PMID 28173822, 2017). "Three deafness-related PSGs might also perform roles in balance and spatial orientation: PDZD7 and GRXCR2 are involved in morphogenesis of the sensory hair cells (‘stereocilia’) in the inner ear, and TECTA encodes a key protein of the tectorial membrane in which the stereocilia are embedded." (PMID 38066641, 2023). "It is notable that the paralogs PDZD7, USH1C, and DFNB31 are all deafness genes and interact with MYO7A." (PMID 27525485, 2016).
hearing loss (7 papers, 2018 to 2025). "Our study enriches the variant spectrum of PDZD7 and suggested that TGE and HTS are reliable tools for genetic testing of hereditary hearing loss for large genes such as PDZD7." (PMID 35715776, 2022). "Intriguingly, a hearing-loss mutation at the N-terminal extension region of the HHD can disrupt the lipid-binding ability of PDZD7 HHD, suggesting that HHD-mediated membrane targeting is required for the hearing process." (PMID 33937240, 2021). "Recently, a novel mutation in PDZD7, p.525_533delDQERGRALLinsV was reported to be associated with non-syndromic hearing loss in the Chinese population." (PMID 33937240, 2021). "Given the scaffolding ability of PDZD7 that facilitates multi-complex interactions, it remains uncertain why biallelic PDZD7 variants manifest only hearing loss." (PMID 31454969, 2019). "In conclusion, we report here for the first time that PDZD7 can act as a disease-causing gene in Korean families, as evidenced by the segregation of recessive inherited moderate-to-severe hearing loss." (PMID 31454969, 2019). "Individuals with de novo heterozygous mutation in PDZD7 exhibit the early onset of hearing impairment and a stronger retinitis pigmentosa compared to siblings without any mutations in PDZD7, suggesting the possible impact of Whrn haploinsufficiency in USH2 development." (PMID 40360853, 2025). "Although recent studies on the other USH genes, PDZD7 and Ush1 g, showed a possibility of haploinsufficiency effect, the potential contribution of heterozygous Whrn loss to hearing loss remains unclear." (PMID 40360853, 2025). "Mutations in PDZD7 are associated with non-syndromic hearing loss and contribute to digenic USH." (PMID 33937240, 2021).
retinal disease (5 papers, 2017 to 2022). "In addition to USH2A variants, mutations in PDZD7 gene (PDZ domain-containing 7) have been proposed to act as a retinal disease modifier in USH2A patients, explaining the frequently observed variability of the visual phenotype." (PMID 33121974, 2020).
Usher syndrome type 2 (4 papers, 2016 to 2025). A syndrome characterized by congenital, bilateral sensorineural hearing loss that is mild to moderate in the low frequencies and severe to profound in the higher frequencies, no abnormalities in the vestibular system, and retinitis pigmentosa. "To date, 31 different pathogenic variants have been reported in the PDZD7 gene, causing ARNSHL, RP or usher syndrome type 2 (USH2)." (PMID 38956522, 2024).
achromatopsia (1 paper, 2024). Achromatopsia (ACHM) is a rare autosomal recessive retinal disorder characterized by color blindness, nystagmus, photophobia, and severely reduced visual acuity due to the absence or impairment of cone function. "WES results showed two variants, a novel null variant (p.Trp548Ter) in the PDE6C gene causing COD type 4 (Achromatopsia) and a previously reported variant (p.Ile84Thr) in the PDZD7 gene causing NSHL." (PMID 38956522, 2024).
autosomal dominant dilated cardiomyopathy (1 paper, 2022). Dilated cardiomyopathy, characterized by dilation and contractile dysfunction of the left and right ventricles, with an autosomal dominant pattern of inheritance. "Pathogenic variants in PDZD7 and RBM20 are associated with autosomal recessive non-syndromic hearing loss and autosomal dominant dilated cardiomyopathy, respectively, suggesting that these variants are unlikely likely to contribute to the clinical presentation." (PMID 35911904, 2022).
choroideremia (1 paper, 2014). Choroideremia (CHM) is an X-linked chorioretinal dystrophy characterized by progressive degeneration of the choroid, retinal pigment epithelium (RPE) and retina. "They included 9 USH genes, 2 candidate USH genes (VEZT and PDZD7), seven hearing-loss genes and the choroideremia-causative gene CHM and the sequencing was carried out on Roche GS Junior sequencer." (PMID 25404053, 2014).
retinitis pigmentosa (1 paper, 2025). Retinitis pigmentosa (RP) is an inherited retinal dystrophy leading to progressive loss of the photoreceptors and retinal pigment epithelium and resulting in blindness usually after several decades. "A patient with a heterozygous frameshift in PDZD7 (another USH2 gene that have high similarity of structure with Whrn) had an earlier onset and more severe retinitis pigmentosa than a sibling without the mutation, suggesting the potential haploinsufficiency effect of USH genes on hearing loss." (PMID 40360853, 2025).
cancer (1 paper, 2022). A tumor composed of atypical neoplastic, often pleomorphic cells that invade other tissues. "Almost all variants of SYNE2, ACAN, and PDZD7 genes identified in our patients had not been shown to be of clinical importance with regard to cancer biology." (PMID 35884495, 2022).
PDZD7 also shares sentences with these, for which no sentence is quoted: Blindness (2 papers); Angelman syndrome (1); breast carcinoma (1); dementia (1); hearing (1); Hearing impairment (1); hepatocellular carcinoma (1); neuropathy (1); non-syndromic hearing loss (1); sensorineural hearing loss (1); Sensory neuropathy (1); Usher syndrome type 1G (1); Usher syndrome type 2A (1).